ADCY1 (adenylate cyclase 1)
Description:
Catalyzes the formation of the signaling molecule cAMP in response to G protein signaling. Mediates responses to increased cellular Ca(2+)/calmodulin levels (By similarity). May be involved in regulatory processes in the central nervous system. May play a role in memory and learning. Plays a role in the regulation of the circadian rhythm of daytime contrast sensitivity probably by modulating the rhythmic synthesis of cyclic AMP in the retina (By similarity).
Synonyms: AC1; DFNB44
Tractability: Small molecule: a high-quality ligand is known; it belongs to a druggable protein family. Antibody: UniProt places it where antibodies can reach, with high confidence; its Gene Ontology location is reachable by antibodies, with high confidence; UniProt predicts a signal peptide or a membrane-spanning region. PROTAC: ubiquitination databases record sites on it; its protein half-life has been measured; a small molecule that binds it is known.
Target class: Enzyme; Lyase
Gene: Protein-coding gene on chromosome 7 (45,574,140 to 45,723,116, forward strand). Ensembl gene ENSG00000164742.
Subcellular location: Membrane; Cell membrane; Cytoplasm; Membrane raft
Subcellular location (Human Protein Atlas): Mitochondria
Pathways (Reactome):
Signal Transduction: Adenylate cyclase activating pathway; G alpha (i) signalling events; G alpha (s) signalling events; G alpha (z) signalling events; GPER1 signaling; Hedgehog 'off' state; PKA activation
Disease: ADORA2B mediated anti-inflammatory cytokines production; FCGR3A-mediated IL10 synthesis
Metabolism: Glucagon signaling in metabolic regulation; PKA activation in glucagon signalling
Neuronal System: Adenylate cyclase inhibitory pathway; CREB1 phosphorylation through the activation of Adenylate Cyclase
Cellular responses to stimuli: High laminar flow shear stress activates signaling by PIEZO1 and PECAM1:CDH5:KDR in endothelial cells
Transport of small molecules: Vasopressin regulates renal water homeostasis via Aquaporins
Gene Ontology:
Molecular function: adenylate cyclase activity; calcium- and calmodulin-responsive adenylate cyclase activity; phosphorus-oxygen lyase activity
Biological process: adenylate cyclase-activating G protein-coupled receptor signaling pathway; cAMP biosynthetic process; cellular response to calcium ion; cellular response to forskolin; cellular response to glucagon stimulus; neuroinflammatory response; positive regulation of long-term synaptic potentiation; regulation of circadian rhythm; renal water homeostasis; vascular endothelial cell response to laminar fluid shear stress; cyclic nucleotide biosynthetic process; intracellular signal transduction; modulation of chemical synaptic transmission; presynaptic modulation of chemical synaptic transmission; system process
Cellular component: extracellular exosome; plasma membrane; cytoplasm; membrane; membrane raft; glutamatergic synapse; hippocampal mossy fiber to CA3 synapse; postsynaptic density; postsynaptic density membrane; presynapse; Schaffer collateral - CA1 synapse
Genetic constraint (gnomAD): Loss-of-function variants: 25 observed, 100.95 expected, observed/expected ratio (o/e) 0.25, 90% interval 0.18 to 0.35. The upper end of that interval is the gene's LOEUF score, 0.35, which puts it in group 1 of 6, group 1 being the genes least tolerant of losing a copy. Missense variants: 866 observed, 1,337.8 expected, observed/expected ratio (o/e) 0.65, 90% interval 0.61 to 0.69. Synonymous variants: 592 observed, 578.58 expected, observed/expected ratio (o/e) 1.02, 90% interval 0.96 to 1.1.
Gene-disease validity (ClinGen):
ClinGen rates the evidence that ADCY1 causes each of these diseases.
nonsyndromic genetic hearing loss (autosomal recessive): Limited. A disease characterized by hearing loss that is not part of a larger syndrome.
Homologues: Orthologues: chimpanzee ADCY1 (99% identical), macaque ADCY1 (99% identical), mouse Adcy1 (92% identical), pig ADCY1 (92% identical), rat Adcy1 (92% identical), dog IGFBP1 (87% identical), guinea pig ADCY1 (78% identical), tropical clawed frog adcy1 (78% identical), zebrafish adcy1a (70% identical), zebrafish adcy1b (54% identical). Paralogues in human: ADCY6 (41% identical), ADCY5 (41% identical), ADCY8 (35% identical), ADCY4 (35% identical), ADCY7 (34% identical), ADCY2 (33% identical), ADCY3 (32% identical), ADCY9 (26% identical), GUCY2D (15% identical), NPR1 (14% identical), GUCY2F (14% identical), NPR2 (14% identical), and 5 more.
Diseases named in the same sentence as ADCY1 in open-access papers:
ADCY1 is named in the same sentence as 79 diseases in open-access papers, as found by Europe PMC text mining. Sharing a sentence is not in itself a finding about the gene and the disease. The quoted sentences say what the papers report.
melanoma (13 papers, 2015 to 2025). A malignant, usually aggressive tumor composed of atypical, neoplastic melanocytes. "Furthermore, previous studies reported that ADCY1 was a key candidate gene in melanoma and rectal adenocarcinoma metastasis." (PMID 34650124, 2021). "Besides, the ADCY1 gene was identified as a key candidate gene involved in melanoma metastasis." (PMID 34134626, 2021). "Our results showed that THOC2 inhibition significantly reduced the expression of PDE4D, PIK3CA, GNAI1, ADCY1, HHIP and ADORA2A in melanoma cells." (PMID 31680623, 2019). "GNAI1, ADCY1 and NR6A1 common target genes involved in the restriction of cAMP signal transduction and of the activation of mTOR pathway signaling were identified among the target genes in the lipid metabolism pathways dysregulated in resistant melanoma cells." (PMID 41550951, 2025). "Two of these DMGs, including ADCY1 and PIK3R1, are related to melanoma metastasis." (PMID 34134626, 2021).
lung carcinoma (7 papers, 2017 to 2024). "We found that the polymorphisms of Adenylate Cyclase 1 (ADCY1) are significantly associated with platinum-based chemotherapy resistance in lung cancer patients in our previous research." (PMID 39338283, 2024). "Here we reviewed for the first time of ADCY1 and its association with drug resistance in lung cancer." (PMID 31839819, 2019). "In recent years, investigations based on genetic sequencing have revealed the emerging role of ADCY1 mutations in affecting drug efficiency in various cancers such as lung cancer, esophageal cancer and colorectal cancer." (PMID 31839819, 2019). "In this review, we summarized the recent advances of ADCY1 in lung cancer and its underlying mechanisms." (PMID 31839819, 2019). "This means that the expression of ADCY1 is diverse between normal cells and lung cancer cells, and it may be associated with cisplatin resistance in lung cancer cells." (PMID 39338283, 2024). "RNA sequencing was used to find the downstream genes affected by ADCY1 which may be associated with drug resistance in lung cancer patients." (PMID 39338283, 2024). "However, the specific mechanism underlying ADCY1 in regulating drug resistance in lung cancer patients is complex and unknown." (PMID 31839819, 2019). "Down-regulating the expression of ADCY1 can increase cisplatin resistance in lung cancer cells through the regulation of the promotion of cell proliferation and the inhibition of cell apoptosis; it can also affect cell cycle activity." (PMID 39338283, 2024). "The higher expression of ADCY1 has a poorer prognosis than the lower expression of ADCY1 in adenocarcinoma of lung cancer patients (p = 0.001)." (PMID 39338283, 2024). "First, we searched the cancer genome atlas (TCGA) database for the expression of ADCY1 mRNA in lung cancer tissues." (PMID 39338283, 2024). "ADCY1 can affect cisplatin resistance in lung cancer cells by regulating cell proliferation, cell apoptosis, and the cell cycle." (PMID 39338283, 2024). "To investigate the effect of ADCY1 on the sensitivity of lung cancer to cisplatin, we used siRNA to interfere with the expression of ADCY1 in human lung adenocarcinoma cell lines A549 and H1299." (PMID 39338283, 2024). "ADCY1 has a higher expression in lung cancer cells than human embryonic lung fibroblast cells (MRC5)." (PMID 39338283, 2024). "We found that the RNA level of ADCY1 and protein expression is significantly higher in lung cancer cells than in MRC5 cells, and it has a lower RNA level of ADCY1 in A549/DDP than in A549 cells (p < 0.001)." (PMID 39338283, 2024). "We discovered that the high expression of ADCY1 can significantly increase cisplatin sensitivity in cisplatin-resistant lung cancer, which is in accordance with the results revealed by the down-regulation of ADCY1 in lung cancer cells." (PMID 39338283, 2024). "In this review, we focus on the function of ADCY1 in the regulation of multidrug resistance in lung cancer mediated by cAMP, which is a second messenger participating in plenty of cellular activities." (PMID 31839819, 2019). "Taken together, ADCY1 is of great significance to be a novel biomarker to predict drug resistance in lung cancer patients." (PMID 31839819, 2019). "Then, we focused our eyes on the downstream effectors of cAMP signaling pathway adjusted by ADCY1, and their relationship with drug resistance in lung cancer." (PMID 31839819, 2019). "ADCY1 has higher expression in lung cancer cells than in normal cells." (PMID 39338283, 2024). "This indicates that the low expression level of ADCY1 may increase cisplatin resistance in lung cancer cells." (PMID 39338283, 2024). "To determine whether the expression of ADCY1 differs between tumor and normal tissues, we searched the RNA sequencing data in the cancer genome atlas (TCGA) database and analyzed the expression differences in the ADCY1 gene in lung cancer patients." (PMID 39338283, 2024).
lung carcinoma (continued). "ADCY1 is overexpressed in nonsmall cell lung cancer and is only accompanied by patient prognosis." (PMID 35832555, 2022). "This indicated that ADCY1 may be a potential biomarker in lung cancer treatment." (PMID 39338283, 2024). "Our study showed that ADCY1 may be a new biomarker in the prognosis of lung cancer patients." (PMID 39338283, 2024). "The upstream signaling molecule of ADCY1 such as forskolin, an activator of ADCY1, can stimulate ADCY1 to catalyze cAMP, can inhibit DNA damage, DNA repair and cell apoptosis which is caused by the degradation of XRCC1 in an Epac-dependent pathway in lung cancer cells." (PMID 31839819, 2019). "We detected the mRNA level and protein expression of ADCY1 in MRC5 and lung cancer cells (A549, H1299, A549/DDP), which showed significant differences between the MRC5 cell and lung cancer cells." (PMID 39338283, 2024). "In lung cancer, ADCY1 can modulate anticancer drugs and regulate apoptosis by regulating the expression of Bcl-2 family proteins, IAPs, and XRCC1 in human lung cancer cells." (PMID 35832555, 2022). "ADCY1 can modulate anticancer drugs and regulate cell apoptosis via the Bcl-2-MOM pathway in lung cancer." (PMID 35832555, 2022). "Further, ADCY1 catalyzes the elevation of cAMP and consequently inhibits the EPAC-dependent pathway degradation of XRCC1-induced DNA damage, DNA repair, and apoptosis in lung cancer cells." (PMID 35832555, 2022). "Six genes showed particularly stronger expression pattern in lung cancer tissues, as compared to normal lungs, which demonstrated that these six genes (GABBR1, PDE4B, PDE4C, ADCY6, ADCY1 and GIPR) had more likelihood of being direct targets of miR-542-5p in lung cancers." (PMID 28927388, 2017). "Furthermore, ADCY1-mediated cAMP can regulate multidrug resistance in lung cancer and other malignancies by regulating the specific long noncoding RNAs (lncRNAs) involved in different signaling pathways." (PMID 35832555, 2022).
depression (6 papers, 2009 to 2021). "The reduced level of Unc13a in both the depression-susceptible and insusceptible groups, and the elevated level of Adcy1 in both the anxiety-susceptible and insusceptible groups were recognized when compared with the control group." (PMID 33627638, 2021). "As an example, the Adenylate Cyclase 1 (ADCY1) gene encodes adenylyl cyclase (AC) primarily expressed in the brain, influences neuroplasticity, as long-term potentiation, depression and memory formation." (PMID 31533613, 2019). "There were no significant alterations in brain expression of any of the other transcripts examined p-values for the in schizophrenia, although ADCY1 was down-regulated in major depressive disorder and bipolar disorder." (PMID 19772658, 2009). "Previously, dysregulated expression of Adcy1 mRNA was identified in the hippocampus and prefrontal cortex of restraint stress induced depression mice, and suggested Adcy1 as a potential biomarkers in depression, and may act as a target in treatment of depression." (PMID 35087377, 2021).
glioma (5 papers, 2017 to 2025). A benign or malignant brain and spinal cord tumor that arises from glial cells (astrocytes, oligodendrocytes, ependymal cells). "High levels of ADCY1 was associated with poor overall survival in patients with metastatic melanoma, glioma, lung and renal tumors but was found downregulated in prostate cancer, osteosarcoma, rectal adenocarcinoma metastasis and pancreatic adenocarcinoma." (PMID 41550951, 2025). "Adenylyl cyclase 1 (ADCY1) overexpression inhibited glioma cell invasion, migration, and proliferation." (PMID 36969015, 2023). "Excluding Adenylate Cyclase 1 (ADCY1), each of the other 18 genes was significantly associated with the prognosis of the gliomas." (PMID 34650975, 2021). "The results revealed that high mRNA expression of ADCY1, ADCY2, and ADCY5 were statistically related to better OS in Glioma patients with P < 0.01, compared with the low expression groups respectively." (PMID 39319137, 2024).
osteosarcoma (4 papers, 2021 to 2025). A usually aggressive malignant bone-forming mesenchymal neoplasm, predominantly affecting adolescents and young adults. "Further in accordance with our results, previous studies have recorded lowered expressions of ADCY1 in rectal adenocarcinoma metastasis, in addition to various human osteosarcomas." (PMID 33744851, 2021). "ADCY1 is down-regulated in prostate cancer and osteosarcoma and may be involved in the development of prostate cancer and osteosarcoma." (PMID 39338283, 2024).
pancreatic adenocarcinoma (4 papers, 2021 to 2025). "It has been reported that ADCY1 can induce β-cell dysfunction in pancreatic cancer; it is a significant diagnostic and prognostic biomarker for pancreatic adenocarcinoma." (PMID 39338283, 2024). "Low expression of ADCY1 was related to pancreatic adenocarcinoma patients’ overall survival, and it was an independent risk factor for pancreatic adenocarcinoma." (PMID 36969015, 2023).
Pancreatic cancer (4 papers, 2021 to 2025). "Overexpression of KIF11 and RCC1 and underexpression of ADCY1 and SDK1 were detected in ~ 60% of grade 2 pancreatic cancer patients and associated with ~ 60% mortality in stages I and II." (PMID 38741142, 2024). "In particular, the overexpression of KIF11 and RCC1 and the underexpression of ADCY1 and SDK1 were detected in ~ 60% of tumor grade 2 pancreatic cancer patients and associated with around 60% mortality in stages I and II, which shows they can be early-diagnosis markers for pancreatic cancer." (PMID 38741142, 2024). "The overexpression of KIF11 and RCC1 and the underexpression of ADCY1 and SDK1 were detected in ~ 60% of tumor grade 2 pancreatic cancer patients." (PMID 38741142, 2024).
rectal adenocarcinoma (4 papers, 2019 to 2025). "ADCY1, adenylate cyclase 1, catalyzes the synthesis of cAMP and was found to be dysregulated in rectal adenocarcinoma (RAC) and other cancers." (PMID 31655798, 2019).
bipolar disorder (3 papers, 2009 to 2023). A disorder of the brain that causes unusual shifts in mood, energy, activity levels and the ability to carry out day-to-day tasks. "Genome-wide association study (GWAS) and linkage study identified Adcy1 and Adcy8 as genetic risk factors for schizophrenia and bipolar disorder, respectively." (PMID 37465213, 2023). "ADCY8 exerts similar functions as ADCY1 and is associated with bipolar disorder and post-traumatic stress disorder in humans." (PMID 35307032, 2022). "In addition, genome wide analysis studies (GWAS) showed that ADCY1 polymorphism was associated with sleep deprivation, schizophrenia and bipolar disorder." (PMID 35307032, 2022).
breast carcinoma (3 papers, 2018 to 2024). "Additionally, our study explored the roles of other hub genes, including BCL2, PLCB1, ADCY1, and GNAO1, within the HER2-positive breast cancer context." (PMID 39682150, 2024).
Cognitive impairment (3 papers, 2019 to 2021). Abnormal cognition is characterized by deficits in thinking, reasoning, or remembering. "Among the significantly enriched signaling pathways from KEGG analysis, oxytocin signaling pathway (PATH:04921; Cacng2, Adcy1, Kcnj4, Kcnj9, Adcy8, Pik3cd, Elk1, Adcy4, Camkk2, Cacng7, Nos3, Kcnj2) may play an important role in the sevoflurane-induced cognitive impairment." (PMID 31582589, 2019). "Furthermore, we demonstrated that inhibition of ADCY1 by carbamazepine can correct abnormal ERK1⁄2 and Akt signaling, protein synthesis, and the core symptoms of cognitive deficits in a mouse model of FXS." (PMID 33297570, 2020). "It is evident that decrease rather than increase of the activity of ADCY1, ERK1⁄2, and Akt shows therapeutic efficacy to correct cognitive impairments in FXS mice." (PMID 33297570, 2020).
mucosal melanoma (3 papers, 2019 to 2025). A melanoma that arises from a mucosal site. "ADCY1 overexpression has been shown to be involved in the migration, invasion, and metastasis of mucosal melanoma, which is commonly found in the mucosa of the head and neck region, followed by anorectal and genital mucosa." (PMID 39941730, 2025).
neuroblastoma (3 papers, 2016 to 2023). Neuroblastoma (NB) is the most common solid, extracranial childhood tumor. "Treatments of SH-SY5Y neuroblastoma cells with 800 and 50 μg/mL of limonene for 24 h significantly influenced ADCY1 expression in different way: high concentrations appear to increase ADCY1 expression, instead low concentrations reduced the ADCY1 expression." (PMID 27649138, 2016).
schizophrenia (3 papers, 2009 to 2023). A major psychotic disorder characterized by abnormalities in the perception or expression of reality. "It is interesting to note that ADCY1 shows high level in cerebellum, cerebral cortex, and thalamus, which are where the schizophrenia risk genes predominantly express." (PMID 36188604, 2022). "Alteration of Adcy1 gene, as suggested by the human genome-wide association study (GWAS), is a potential genetic risk factor for schizophrenia." (PMID 36188604, 2022). "Although how ADCY1 regulates the hallmark schizophrenia symptoms remains unclear, ADCY1 deficiency leads to impaired LTP and spatial memory and maldevelopment of the sensory cortex." (PMID 36188604, 2022). "As defective cortico-cerebellar-thalamic-cortical circuit is suggested as an emerging etiological factor for schizophrenia, the region-specific function of ADCY1 needs to be studied." (PMID 36188604, 2022).